LSM3 (LSM3 homolog, U6 small nuclear RNA and mRNA degradation associated)
Description:
Plays a role in pre-mRNA splicing as component of the U4/U6-U5 tri-snRNP complex that is involved in spliceosome assembly, and as component of the precatalytic spliceosome (spliceosome B complex). The heptameric LSM2-8 complex binds specifically to the 3'-terminal U-tract of U6 snRNA.
Synonyms: YLR438C; SMX4; USS2
Tractability: Small molecule: a structure with a bound ligand is known. PROTAC: ubiquitination databases record sites on it; its protein half-life has been measured.
Gene: Protein-coding gene on chromosome 3 (14,178,801 to 14,201,122, forward strand). Ensembl gene ENSG00000170860.
Subcellular location: Nucleus
Subcellular location (Human Protein Atlas): Nucleoli; Nucleoplasm
Pathways (Reactome):
Metabolism of RNA: mRNA Splicing - Major Pathway; mRNA decay by 5' to 3' exoribonuclease
Gene Ontology:
Molecular function: protein binding; RNA binding; U6 snRNA 3'-end binding
Biological process: mRNA splicing, via spliceosome; deadenylation-dependent decapping of nuclear-transcribed mRNA; mRNA processing; P-body assembly; spliceosomal snRNP assembly; spliceosomal tri-snRNP complex assembly
Cellular component: catalytic step 2 spliceosome; cytoplasm; Lsm2-8 complex; nucleus; precatalytic spliceosome; spliceosomal complex; U2-type precatalytic spliceosome; U4/U6 x U5 tri-snRNP complex; cytosol; Lsm1-7-Pat1 complex; nucleoplasm; P-body; U4/U6 snRNP; U4atac/U6atac snRNP; U4atac/U6atac x U5 tri-snRNP complex; U6 snRNP; U6atac snRNP
Genetic constraint (gnomAD): Loss-of-function variants: 9 observed, 7.47 expected, observed/expected ratio (o/e) 1.2, 90% interval 0.71 to 1.85. That is too few expected variants to judge how well the gene tolerates losing a copy. Missense variants: 69 observed, 107.28 expected, observed/expected ratio (o/e) 0.64, 90% interval 0.53 to 0.79. Synonymous variants: 36 observed, 39.67 expected, observed/expected ratio (o/e) 0.91, 90% interval 0.69 to 1.2.
Homologues: Orthologues: chimpanzee LSM3 (100% identical), guinea pig LSM3 (100% identical), mouse Lsm3 (100% identical), rabbit LSM3 (100% identical), rat Lsm3 (100% identical), dog LSM3 (98% identical), zebrafish lsm3 (97% identical), pig LSM3 (96% identical), tropical clawed frog lsm3 (96% identical), macaque LSM3 (93% identical), Drosophila melanogaster LSm3 (77% identical), Caenorhabditis elegans lsm-3 (70% identical).
Diseases named in the same sentence as LSM3 in open-access papers:
LSM3 is named in the same sentence as 20 diseases in open-access papers, as found by Europe PMC text mining. Sharing a sentence is not in itself a finding about the gene and the disease. The quoted sentences say what the papers report.
cervical carcinoma (5 papers, 2018 to 2023). A carcinoma arising from either the exocervical squamous epithelium or the endocervical glandular epithelium. "LSM3 expression was correlated with progression-free survival and strongly associated with the metastatic phenotype of cervical carcinoma." (PMID 36371223, 2022). "LSM3 was found to be downregulated in cervical cancer and associated with poor progression-free survival outcome." (PMID 34638387, 2021). "LSM3 was found downregulated in cervical cancer, correlating with progression free survival." (PMID 32454908, 2020). "Consistently, other studies revealed LSM1, LSM2, LSM3, LSM12 as oncogenes which could play a crucial role in growth and progress of breast cancer, basal-like primary tumors, cervical carcinoma or colorectal cancer." (PMID 37007092, 2023).
breast carcinoma (3 papers, 2021 to 2023). "We have previously reported that LSM3 can serve as a subtype‐specific biomarker in basal‐like breast cancer." (PMID 37559353, 2023). "In colorectal cancer, LSM3 was also significantly associated with lymphatic metastasis, however, similar reports in breast cancer are lacking." (PMID 34638387, 2021).
colorectal cancer (3 papers, 2020 to 2023). A primary or metastatic malignant neoplasm that affects the colon or rectum. "In colorectal cancer, LSM3 also was significantly associated with lymphatic metastasis, but in EC, there is still no report." (PMID 32454908, 2020).
Cognitive impairment (2 papers, 2020 to 2023). Abnormal cognition is characterized by deficits in thinking, reasoning, or remembering. "Abnormal expression of LSM3 has been found to be associated with mild cognitive impairment (MCI) and Alzheimer’s disease (AD)." (PMID 37686279, 2023). "Therefore, abnormal expression of LSM3 might contribute to cognitive impairment." (PMID 32308643, 2020).
Ataxia syndrome (1 paper, 2023). "In addition to being identified as a gene that links MCI progressing to AD, LSM3 has been implicated in PD, AD, the adult-onset neurodegenerative disorder Fragile X Tremor and Ataxia syndrome." (PMID 37834458, 2023).
metastatic disease (1 paper, 2006). "Furthermore, when gains and losses of MRPS23 and LSM3 occur, they may influence the gene expressions and possibly the development of metastatic disease." (PMID 17054779, 2006).
pancreatic cancer (1 paper, 2006). "LSM3 and TBX3 may also participate in cell cycle control; upregulation of LSM3 promotes proliferation of pancreatic cancer cells, and TBX3 may interact with the cell cycle protein CDKN2A." (PMID 17054779, 2006).
prostate carcinoma (1 paper, 2023). A carcinoma that arises from epithelial cells of the prostate gland. "Notably, the results showed that LSM3 and DHX16 were significantly associated with the fitness of prostate cancer cells, suggesting that these two SFs might be involved in controlling key processes for tumour cell survival and proliferation." (PMID 37559353, 2023). "Through such comprehensive approaches, the roles of LSM3 and DHX16 in prostate cancer progression can be better understood." (PMID 37559353, 2023). "Further molecular biology investigations are suggested to elucidate LSM3 and DHX16's mechanisms in prostate cancer progression." (PMID 37559353, 2023).
tumor (4 papers, 2006 to 2023). "Similarly, LSM3 expression was correlated with tumor purity (r = 0.191, p = 1.29 × 10−9) and CD4+ T-cell markers (r = −0.143, p = 8.24 × 10−6)." (PMID 34638387, 2021). "In Her-2 BRCA, LSM3 and SNU13 were significantly upregulated in tumor samples and both genes were negatively correlated with prognosis." (PMID 34630526, 2021). "One group was associated with rapid proliferation, oxidative phosphorylation, invasiveness, and tumor size (MRPS23, MRPL11, CKS2, LSM3, TBX3, MSN) and another with hypoxia tolerance, anaerobic metabolism, and high lactate content (PDK2, KLF3)." (PMID 17054779, 2006).
LSM3 also shares sentences with these, for which no sentence is quoted: adenoid cystic carcinoma (1 paper); Alzheimer disease (1); cancer (1); colon cancer (1); esophageal carcinoma (1); lung adenocarcinoma (1); Lymphatic Metastasis (1); Lynch syndrome (1); metastasis (1); stomach adenocarcinoma (1); uterine corpus endometrial carcinoma (1).